GRPR (gastrin releasing peptide receptor)
Diseases named in the same sentence as GRPR in open-access papers (continued):
Sharing a sentence is not in itself a finding about the gene and the disease.
cancer (continued). "Background/Objectives: Gastrin-releasing peptide receptor is a promising target for cancer diagnosis and therapy." (PMID 40283887, 2025). "GRPR is notably overexpressed in several cancers, including small-cell lung cancer (SCLC), breast cancer, exocrine tumors, and some glioblastomas, with expression levels exceeding 70% in SCLC." (PMID 40428099, 2025). "GRPR-targeting radiopeptides seem to be promising, due to the high-density expression in several human cancers and the relatively low physiological expression in healthy tissues." (PMID 40647404, 2025). "A number of GRPR radioligands have been evaluated preclinically and clinically for the diagnosis and therapy of varying human cancers." (PMID 40430268, 2025). "Radiolabeled bombesin analogs have been proposed and evaluated for imaging and therapy of GRPR-expressing cancers." (PMID 40871022, 2025). "Overall, this study supports the advancement of GRPR-targeted peptide therapeutics as a novel and versatile strategy for treating aggressive cancers such as SCLC." (PMID 41226822, 2025). "Gastrin-releasing peptide receptor (GRPR) is overexpressed in several cancers, including prostate and breast, making it an attractive target for radiopharmaceutical development." (PMID 40775579, 2025). "At present, several radiolabeled ligands targeting GRPR have been introduced into clinical practice for cancer diagnostics and radioligand therapy." (PMID 41684873, 2025). "Overexpressed in many solid malignancies, gastrin-releasing peptide receptor (GRPR) is a promising target for diagnosis and radioligand therapy of GRPR-expressing cancers." (PMID 40283887, 2025). "GRPR expression in cancer and control samples was assessed by immunohistochemistry using an anti-GRPR antibody developed by Ziel Biosciences, Brazil." (PMID 41266536, 2025). "Both conjugates were effectively internalized; however, only Hemiasterlin conjugates inhibited cancer cell proliferation, establishing their cytotoxic potential against GRPR/BB2-expressing lung cancer cells." (PMID 40428099, 2025). "Background/Objectives: Overexpressed in various solid tumors, the gastrin-releasing peptide receptor (GRPR) is a promising target for cancer diagnosis and therapy." (PMID 40006047, 2025). "The gastrin-releasing peptide receptor (GRPR) is a well-established target in preclinical and clinical cancer research." (PMID 40141329, 2025). "Since GRPR expression in normal tissues is largely restricted to the pancreas and gastrointestinal organs, targeting this receptor enables early detection of cancer lesions with high specificity." (PMID 40775579, 2025). "Given the upregulation and relevance of the GRPR in cancer, this work aims to develop an immunotheranostic approach using TMs derived from the bombesin antagonist BBN2 in monomeric and dimeric forms." (PMID 40141329, 2025). "Both pan-carcinoma overexpression of GRPR and the demonstration of its radionuclide visualization feasibility prompted active research and development of targeting agents for radionuclide diagnostics and therapy of GRPR-expressing tumors." (PMID 40871022, 2025). "The researchers developed bis-deoxygalactosyl-carborane, a carborane-functionalized GRPR agonist that selectively binds to GRPR 83, a receptor that is overexpressed in many types of cancer." (PMID 38961887, 2024). "GRPR acts as a growth factor in an autocrine manner, playing a critical role in promoting cancer metastasis and angiogenesis in various cancers." (PMID 39768218, 2024). "Gastrin-releasing peptide receptor (GRPR) is overexpressed in various cancers and is a promising target for cancer diagnosis and therapy." (PMID 38794191, 2024). "GRPR contributes to tumor growth and progression and is overexpressed in various cancers, including prostate, breast, small cell lung (SCLC), colon, gastrointestinal, and pancreatic cancer, as well as glioblastomas and neuroblastomas." (PMID 39598465, 2024).
cancer (continued). "Overall, these findings highlight the potential of dual-targeting radiotracers that focus on αvβ3 integrin and GRPR to improve the accuracy of cancer diagnosis and staging in specific cancer types." (PMID 39598465, 2024). "PD176252, the first synthesized small-molecule GRPR antagonist, has been identified as a potent receptor ligand capable of inhibiting the tumorigenesis of cancer cells." (PMID 39768218, 2024). "Radiolabeled bombesin (BBN) analogs exhibit high binding affinity and specificity to GRPR, and its research in the field of GRPR-positive cancer therapy has been thriving." (PMID 38195680, 2024). "GRPR is also found overexpressed in several solid malignancies, such as prostate, breast, colon, and lung cancers, and is involved in the malignant neoplasm’s development by coupling with phospholipase C and activating protein kinase C." (PMID 38999054, 2024). "One more investigation has shown Ga-labeled GRPR antagonist as a promising agent for cancer imaging." (PMID 39539754, 2024). "Overexpressed in various solid tumors, gastrin-releasing peptide receptor (GRPR) is a promising cancer imaging marker and therapeutic target." (PMID 38305955, 2024). "The overexpression of GRPR in various tumors makes it a promising target for the design of targeted radiopharmaceuticals for diagnosis and radioligand therapy of GRPR-expressing cancers." (PMID 38305955, 2024). "Preliminary in vitro experiments revealed that, depending on the linker and the presence of a lipid tail, these novel PDCs possess good to potent anticancer activity and moderate selectivity for GRPR-overexpressing cancer cells." (PMID 39600359, 2024). "In the past two decades, many radiolabeled GRPR-targeted ligands have been developed, and some of them have been translated into the clinic for cancer diagnosis and radioligand therapy." (PMID 38999054, 2024). "Our data suggest that [68Ga]Ga-LW02050 is a promising PET tracer for detecting GRPR-expressing cancer lesions." (PMID 38999054, 2024). "Although they do not trigger receptor activation upon binding, these antagonists effectively target and remain in GRPR-expressing cancer lesions while quickly clearing from normal organs in both animals and humans." (PMID 38708130, 2024). "This review summurized the advances of GRPR-targeted radiotracers for the diagnosis and treatment of cancers, paving the way for significant transformations in clinical practice." (PMID 38279185, 2024). "Overexpression of GRPR has been reported to induce cancer cell proliferation and facilitate malignant neoplasm development." (PMID 38305955, 2024). "Initially, radiolabeled bombesin analogues were created to target GRPR-positive tumors in vivo, primarily due to their rapid and extensive internalization into cancer cells." (PMID 38279185, 2024). "These bombesin derivatives were tested for their gastrin-related peptide receptor (GRPR)-mediated internalization into cancer cells using flow cytometry, proving that the lipid tail (especially C14) enhances the cell internalization." (PMID 39600359, 2024). "Owing to its overexpression in malignant tissues, GRPR is a promising target for cancer imaging and therapy." (PMID 38999054, 2024). "Recent studies have revealed the potential of radiolabeled GRPR antagonists for therapeutic applications in human cancer." (PMID 38366299, 2024). "The role of gastrin-releasing peptide receptor (GRPR) in various diseases, including cancer, has been extensively studied and has emerged as a promising therapeutic target." (PMID 39327021, 2024). "Previous studies have primarily focused on using GRPR-targeted drugs for molecular imaging and monitoring cancer recurrence or metastasis." (PMID 39768218, 2024). "The gastrin-releasing peptide receptor (GRPR) is a G-protein coupled receptor that has been investigated as an attractive target for the detection and treatment of several cancer types, including PCa." (PMID 37719014, 2023).
cancer (continued). "With overexpression in various cancers, the gastrin-releasing peptide receptor (GRPR) is a promising target for cancer imaging and therapy." (PMID 36838968, 2023). "The high pancreas uptake limits the application of these GRPR-targeting radiopharmaceuticals for detecting cancer lesions adjacent to or located in the pancreas and lowers the maximum tolerated dose for targeted radioligand therapy to minimize toxicity." (PMID 36838968, 2023). "These ligands were confirmed to be GRPR antagonists, and some were proven to have very promising binding affinities toward GRPR (Ki at pM scale) and the ability to inhibit cancer cell proliferation." (PMID 36838968, 2023). "GRPR-targeting bombesin peptide allowed the selective accumulation of the probe in PC-3-KD1 cancer cells in vitro, as shown in the receptor saturation study." (PMID 36834867, 2023). "Due to its overexpression in these cancer types, radiotracers targeting the GRPR have been developed for peptide receptor radionuclide imaging and therapy (PRRT)." (PMID 37584725, 2023). "A possible role of ER on the modulation of GRPR expression by cancer cells, as previously reported for PC." (PMID 38020178, 2023). "All clinical studies demonstrated the safety of the tracers, as well as the high-contrast imaging of GRPR expression in both types of cancers." (PMID 36980517, 2023). "The GRPR is also over-expressed in other cancers; gastrinomas (about 100%), colon (30–50%), renal, small cell lung, and uterine cancers overexpress GRPRs." (PMID 36980517, 2023). "In particular, the compound was demonstrated to be more effective than PTX or 177Lu alone while the interaction between BN and GRPr guaranteed a selective uptake of cancer cells." (PMID 36986728, 2023). "Oncological GRPR targeting represents a promising direction of research, from which the modern cancer management battlefield can benefit a lot." (PMID 36834867, 2023). "Beside the somatostatin receptor and the PSMA, GRPR is a highly promising target for the development of novel theranostic compounds, due to the high-density expression in several human cancers and the relatively low physiological expression in healthy tissues." (PMID 38020178, 2023). "GRPs and BBN share the same heptapeptide sequence at the C-terminus, which has been used as the targeting vector for the design of GRPR-targeting radiopharmaceuticals for cancer diagnosis and radioligand therapy for decades." (PMID 36838968, 2023). "GRPr is overexpressed in different cancers, such as breast cancer, small-cell lung cancer, and gastrointestinal stromal tumors." (PMID 38201600, 2023). "Next to the physiological expression, overexpression of GRPR has been reported in various cancer types, including lung-, breast- (BC), pancreatic-, prostate- (PCa), head and neck cancer, and neuroblastomas/glioblastomas." (PMID 37584725, 2023). "For example, gastrin-releasing peptide receptor (GRPR) acts as an inflammatory factor, and GRPR antagonists induce senescence and antiproliferative effects in several cancers." (PMID 36396833, 2022). "The gastrin-releasing peptide receptor (GRPR) is a G-protein-coupled receptor that is overexpressed in many solid cancers and is a promising target for cancer imaging and therapy." (PMID 35744904, 2022). "Our results provided an important proof of concept toward the development of bioorthogonal approaches to GRPR-expressing cancers, which are worth investigating further to improve the in vivo results." (PMID 36559063, 2022). "GRPR is highly overexpressed in several cancers including PC, especially in earlier stages, making it an attractive target for initial staging." (PMID 36057766, 2022). "GRPR (also known as bombesin receptor 2 (BB2)) is a transmembrane receptor expressed on the surface of many cancers and is overexpressed in most PCa." (PMID 36077820, 2022).
cancer (continued). "To demonstrate the potential for clinical translation of [68Ga]Ga-TacsBOMB5 to detect GRPR-expressing cancers, we conducted head-to-head comparisons with the clinically validated [68Ga]Ga-RM2." (PMID 35744904, 2022). "The overexpression of GRPR in malignant tissues has prompted development in GRPR-targeting radiopharmaceuticals for better management of GRPR-expressing cancers." (PMID 35744904, 2022). "Another promising target is the gastrin releasing peptide receptor (GRPR) which is highly overexpressed in several cancers including PC with favorable characteristics for initial staging of PC." (PMID 36057766, 2022). "Despite its disadvantages, [64Cu]Cu-labelled GRPR antagonist D-Phe-Gln-Trp-Ala-VaI-Gly-His-Sta-Leu-NH2 conjugated either to NOTA or NODAGA was reported to possess considerable value in the PET imaging of GRPR-expressing malignancies at preclinical level." (PMID 36077458, 2022). "Cluster 3 has 9 nodes and 36 edges, including the GRPR (gastrin-releasing peptide receptor) which is known to be expressed in numerous cancers." (PMID 34512870, 2021). "The resulting radioligands behaving as typical GRPR-agonists bound to the GRPR and rapidly internalized in cancer cells after intravenous injection (iv)." (PMID 34680243, 2021). "The Gastrin Releasing Peptide-Receptor (GRP-R) is a G-protein coupled receptor of the bombesin receptor family that show great potential for imaging and therapy of many cancers." (PMID 34452121, 2021). "Many studies have highlighted that the GRPR pathway is a key actor of cancer progression through increasing proliferation, invasion and migration of cancer cells via autocrine and paracrine pathways." (PMID 33801382, 2021). "NeoB is a radiotracer targeting the gastrin-releasing peptide receptor (GRPR), a G-protein–coupled receptor expressed in various cancers." (PMID 33801382, 2021). "Extended and systematic structure-activity relationship studies have pinpointed candidates eligible for clinical translation in breast, prostate, and other GRPR-positive cancer patients, applying SPECT/CT, or PET/CT imaging and PRRT." (PMID 34830920, 2021). "The expression of gastrin releasing peptide receptors (GRPRs) in a series of human tumors has provided the rationale for the application of anti-GRPR peptide radioligands in cancer diagnosis and therapy following a patient-tailored theranostic approach." (PMID 34680243, 2021). "Gastrin releasing peptide receptor (GRPR) is a G-protein coupled receptor overexpressed in different types of cancer including PCa." (PMID 34829417, 2021). "The overexpression of GRPR in several cancers makes it an attractive candidate for imaging and targeted therapy." (PMID 33801382, 2021). "Such pioneer clinical studies have been eye-openers with regards to the strengths and limitations of GRPR-positive cancer theranostics, revealing new challenges to be met." (PMID 34830920, 2021). "Keeping a strong focus on theranostics of GRPR-positive cancer, we limit this review to peptide analogs labeled with diagnostic or therapeutic radiometals, excluding the F-18 analogs suitable for PET imaging only." (PMID 34830920, 2021). "Since then, most of these radiolabeled analogues have been designed as GRPR agonists with a favorable internalization in cancer cells." (PMID 33669938, 2021). "The growth stimulatory effects of bombesin agonists in several human cancers have triggered systematic efforts to develop GRPR antagonists as antitumoral drugs, capable of binding to the receptor with a high affinity without it being activated." (PMID 34830920, 2021). "After briefly outlining the issue of metabolic stability, the new trends in GRPR-targeted cancer theranostics are described, revealing the challenges and new opportunities in the field." (PMID 34830920, 2021). "Women have a reduced DNA repair capacity and increased gastrin-releasing peptide receptor (GRPR) that stimulate cancer cell proliferation." (PMID 34079807, 2021).
cancer (continued). "The bombesin subfamily is the best studied GRPR, and a large number of mammalian and amphibian bombesin peptide analogs have been radiolabeled for cancer imaging and therapy." (PMID 32582550, 2020). "In fact, a general concern in the application of GRPR radioligands for cancer theranostics has been the high-density expression of GRPR not only on tumors, but also in physiological tissues, especially in the pancreas." (PMID 32731473, 2020). "Clinical trials have also been performed with the GRPr agonist AMBA, labelled with gallium-68 and lutetium-177 in patients with various cancers, to assess its applicability as diagnostic as well as therapeutic radiopharmaceutical." (PMID 33258012, 2020). "Gastrin releasing peptide receptor (GRPR) is a G-protein coupled receptor of the bombesin family expressed in most human cancers and represents an appealing biomarker for imaging and therapy of tumors." (PMID 31652624, 2019). "Its cognate receptor, gastrin releasing peptide receptor (GRPR), is widely expressed in cancers of the lung, pancreas and ovaries." (PMID 31921534, 2019). "In contrast to amphibian BBN-like motifs, the respective human homologs have surprisingly remained unexploited as radionuclide carriers for targeting GRPR-positive cancer." (PMID 30897789, 2019). "The gastrin-releasing peptide receptor (GRPR) has attracted much attention in cancer diagnosis and therapy." (PMID 30871262, 2019). "For example, the Gastrin Releasing Peptide Receptor (GRPR) is overexpressed in various cancer type cells and was suggested to play a significant role in metastasis." (PMID 29861840, 2018). "Peptide antagonists such as RC-3095 or (Psi13, 14, Leu14)BB blocked the GRPR, and they inhibited the growth of cancer cells." (PMID 30008698, 2018). "We found that the gastrin-releasing peptide receptor, which is implicated in EGFR-associated cancers, also triggered iRhom2 phosphorylation." (PMID 29045841, 2017). "The overexpression of GRPR in a variety of cancer types provides opportunities for diagnosis and therapy by means of peptide-radiopharmaceuticals directed to GRPR-positive lesions." (PMID 29137110, 2017). "Over the past years, multiple GRPR-targeting radioligands have been described to target GRPR-expressing cancers." (PMID 28134770, 2017). "Since GRPR is over-expressed in a wide variety of cancers, bombesin analogue peptides were used extensively for cancer imaging, for detection of cancer." (PMID 27827443, 2016). "ProCA1.GRPR exhibits several unique capabilities for in vivo molecular imaging of GRPR for cancer detection." (PMID 26577829, 2015). "ProCA1.GRPR is expected to have important preclinical and clinical implications for the early detection of cancer and for monitoring treatment effects." (PMID 26577829, 2015). "The discovery of GRPR overexpression in cancer cells led to the test of specific GRP analogues for imaging or targeted therapy." (PMID 26097883, 2015). "Several emergent studies point to the potential of GRPR as a therapeutic target, supporting its role as an important player of signaling pathways in cancer cells, namely cell proliferation, metastasis and angiogenesis." (PMID 26097883, 2015). "The overexpression of gastrin-releasing peptide receptor (GRPR) in cancer can be used for peptide-receptor mediated radionuclide imaging and therapy." (PMID 25036155, 2014). "Human GRPR is upregulated by the recruitment of the transcription factor CRE-binding protein (CREB) to a cAMP-response element (CRE)-binding site within the GRPR promoter in cancer cells." (PMID 24349381, 2013). "In contrast, only 41 (38%) of the 107 cancer-free surgical controls had detectable GRPR bronchial expression." (PMID 22296774, 2012). "Our 1997 report indicated that of the 4 cancer-free subjects with defined bronchial GRPR expression and smoking status, 1 active smoker was GRPR positive while 3 subjects who were former or never smokers were negative for GRPR expression." (PMID 22296774, 2012).